IL6 (interleukin 6)
Diseases named in the same sentence as IL6 in open-access papers (continued):
Sharing a sentence is not in itself a finding about the gene and the disease.
infection (continued). "However, in the GK1.5 group, IL-6 levels were significantly reduced compared to the EV group, indicating that the expression of GK1.5 on exosome surfaces improved its targeting and infection efficiency, thus promoting the function of mFoxp3 and reducing the inflammatory response." (PMID 40284659, 2025). "During infection with a mutant Salmonella Typhimurium strain where the GBS of SarA was replaced with the GBS from gp130 (psarA:gp130), the level of phosphorylation never reached the level seen with wild-type SarA and was more similar to the level seen with IL-6 stimulation." (PMID 40188438, 2025). "Likewise, fully differentiated NHBE cells infected with avian influenza viruses induce robust IP-10, IL-6, and RANTES responses early during infection compared to human H3N2 infection, as well as inhibition of the MCP-1 chemokine relative to mock-infected NHBE cells." (PMID 39791909, 2025). "BR15 infection induced a modest but statistically significant increase in TNF-α expression (p < 0.05) and a significantly higher expression of IFN-β1, IL-1β, IL-6, and IL-10, as well as the chemokines CCL2 (MCP-1), CCL5 (RANTES), and CXCL8 (IL-8), compared to MR766-infected cells." (PMID 40732762, 2025). "Especially in the case of the proinflammatory cytosine TNF-α, there seems to be a close correlation with infections with atypical pathogens and a marked immune response, as well as with increased IL-1β and IL-6 values compared with the absence of infection (both in the presence and absence of PCOS)." (PMID 40647668, 2025). "The study concluded TNF-α lacked specificity for bacterial etiology and could not discriminate infection severity, reinforcing its limited clinical utility compared to IL-6/IL-10." (PMID 40647525, 2025). "This is interesting since tocilizumab has often been associated with an increased risk of infection, yet in our findings from real-world data, tocilizumab/sarilumab showed a lower rate of post-treatment infections requiring hospital treatment compared with non-anti-IL-6 bDMARDs." (PMID 39698233, 2025). "Although IL-6 was essential for the awakening and the initial marked expansion of DCCs, minimal levels of IL-6 were detected in BALF of MMTV-Her2 mice 15 dpi, indicating the presence of other factors that promote persistence after the expansion of DCCs at later times post-infection." (PMID 40739350, 2025). "GB37 infection significantly induced IL-6 and MIP-1α in gestational membranes and IL-6 in the fetal chamber of the organ-on-a-chip device compared to uninfected controls; however, GB37 infection resulted in significantly less cytokine production compared to GB112 infection in several samples." (PMID 41277827, 2025). "In the present study, Compared with Met and Mer, HC treatment can significantly improve the infection of patients with DFU, and it could significantly reduce the expression levels of inflammatory factors (TNF-α and IL-6) in the serum of patients, and reduce the inflammatory response of patients." (PMID 40745559, 2025). "pullorum infection significantly elevated (p < 0.05) the renal (CREA, UREA), hepatic (ALT, AST), immunological (IgG, IgM), and inflammatory (TNF-α, IL-6, SAA, CRP) parameters, as well as the expression of trefoil factor 3, Toll-like receptor 2, TNF-α, IL-1β, and IL-6." (PMID 41597538, 2025). "For example, a rise in serum IL-6 levels after sterile surgical procedures has been shown to precede the increase of body temperature and acute-phase proteins, highlighting its predictive value even when infection is not yet clinically evident." (PMID 40806991, 2025). "Presepsin still showed the highest AUC value at 72 h before fever onset when comparing febrile neutropenia and non-FN patients, followed by IL-6, which may be related to its earliest peak levels during infection." (PMID 40961458, 2025).
infection (continued). "In a mouse infection model, the carmofur treatment group showed a reduction of approximately two log levels in bacterial load in lung tissue and blood, a significant decrease in the levels of inflammatory cytokines TNF-α and IL-6, and an improvement in survival rate to 60%." (PMID 40149043, 2025). "Although HepEVs did not significantly reduce the release of IL-6 compared to NTHi infected controls, CepEVs did significantly increase this release compared to HepEVs, suggesting CepEVs further exacerbate the release of IL-6 in response to NTHi infection." (PMID 41550953, 2025). "IL-6 was induced in the lung upon infection at 3 dpi but did not vary significantly among groups." (PMID 40854598, 2025). "However, at 72 hours post-infection, the expression of IL-17, IFN-γ, T-bet, RORγt, and IL-6 genes was markedly reduced in the Pm_OMVs-infected group compared to the Pm group (P < 0.01), whereas the expression levels of TGF-β, GATA-3, IL-4, and FoxP3 were significantly increased (P < 0.01)." (PMID 41306977, 2025). "As part of the inflammatory response to infection, IL-6 is secreted by lymphoid and non-lymphoid cells and, in the case of periprosthetic joint infection, high concentrations of this cytokine have been measured not only in the sera of patients but also locally in the synovial fluid." (PMID 40981112, 2025). "Moreover, BA.2 virus infection significantly increased secretion of IFN-λ1, IFN-λ2, IFN-λ3, IL-6, and IL-1RA in HNECs relative to D614G infection, but not in IPSC-LOs." (PMID 40295859, 2025). "Thus, we can say that the infection can influence significantly the IL-6 and CRP values, but these values are not sensitive to the smoking habit." (PMID 40242671, 2025). "Furthermore, an increased concentration of the pro-inflammatory cytokine TNF-α was found in the lungs of TRαKO mice at the peak of infection, whereas other cytokines, e.g. IL-1β and IL-6, were not altered." (PMID 41159501, 2025). "However, we routinely noted an increase in serum IL-6 and IL-10 in both the A/J and WT B6 mice at peak infection with the Ig::Tn NMII strain, which could potentially be related to infection of adipocytes." (PMID 40586810, 2025). "In addition, mangiferin was found to modulate host immune responses by simultaneously inhibiting pro-inflammatory cytokines, IL-6 and TNF-α, and upregulating the expression of anti-inflammatory IL-10 and antiviral IFN-γ, thus mitigating infection-induced inflammation." (PMID 40733492, 2025). "Importantly, the frequency of Tem was associated with elevated levels of inflammatory cytokines in the sera (primarily interleukin (IL)-1β and IL-6), suggesting a potential link between the process of inflammation and the fate of CD4 T cells in 17ZR101 infection." (PMID 40096073, 2025). "Notably, infection-induced dysregulation of immune-related genes (e.g., TXNIP, HO-1 and Prdx5) has been reported, while deletion of the gntR10 gene elevates levels of TNF-α, IL-6 and IL-8 transcripts in infected cells." (PMID 41235247, 2025). "Infection with PLP1-deficient parasites resulted in drastically reduced TNF-α and IL-6, resolved infection-driven IFN-γ production, and failed to result in exaggerated cytokine and chemokine responses associated with proinflammatory overproduction and host mortality." (PMID 40166190, 2025). "Similarly, replicating IAV induced secretion of TNFα and IL-6 from DCs but not in the presence of WT and H84T that inhibit infection." (PMID 40333697, 2025). "Infection with either virus did not alter Il6 expression more than 2-fold." (PMID 40133326, 2025). "Hence, aberrant interactions between IL-6 and CO2-sensing regions in the brainstem may contribute to impaired responses to hypercapnia generated by infection combined with prone sleeping position and rebreathing." (PMID 40013115, 2025). "Furthermore, IL-1β and IL-6 are major proinflammatory cytokines released by diverse immune and nonimmune cells upon stimulation, such as infection, injury, and stress." (PMID 39949769, 2025).
infection (continued). "Similarly, IL-6 levels can be affected by non-infectious inflammatory processes, which reduces its specificity as an infection marker." (PMID 40806991, 2025). "Furthermore, research tends to prioritize a limited subset of inflammation-related cytokines, such as IL-6, IL-8, and TNF-α, which are associated with generalized immune responses rather than specific infection states." (PMID 40137168, 2025). "Interleukin-1β (IL1B), interleukin-6 (IL6), tumor necrosis factor (TNF), and interferon-β (IFNB1), as key components of this response, have important functions in initial detection of Mtb, controlling infection, initiating effective T cell responses, and modulating immunopathology." (PMID 40402573, 2025). "In contrast, infection with all tested Brucella species did not increase IL-6 production." (PMID 40943115, 2025). "Notably, IL-6 inflammatory factor, CASP8, and APOA1 may also be the key genes with altered expression after pathogen infection, which are closely related to the inflammatory response to tracheal injury in calves." (PMID 40005807, 2025). "Precise patient selection based on simple, clinically available indicators (e.g., IFN-I/IL-6 signatures or markers of mitochondrial damage) and methodological caution will be crucial, as non-selective TLR blockade may carry a risk of infection." (PMID 41303627, 2025). "Furthermore, to date, there is a lack of data regarding ascites IL-6 levels in patients afflicted with infections other than SBP." (PMID 38962151, 2024). "Additionally, mRNA levels of pro-inflammatory cytokines including IL-6, TNF-α, IL-1β, and IL-8 were significantly reduced in BALB/cTFE3-/- mice relative to BALB/cTFE3+/+ mice, suggesting a critical role of TFE3 in viral replication and infection." (PMID 39652582, 2024). "Serum IL-6 levels were also higher among those with active infections than those with positive Sh serologies without active infection and in individuals with Sh infection with urinary tract pathology, supporting a likely role of IL-6 in the pathogenesis of urogenital schistosomiasis." (PMID 39250522, 2024). "However, at 48 h post infection there was no decrease in IL-6 levels but a significant decline in IL-12p40." (PMID 38698289, 2024). "In addition, the mRNA expression levels of proinflammatory cytokines downstream of the RIG-I/MDA5 pathway, including IL-6, IL-8 and TNF-α, were also significantly upregulated in the infection group than that in the control group at 12 hpi, 24 hpi and 48 hpi, respectively." (PMID 39502173, 2024). "Furthermore, only infection with Omicron resulted in a significant induction of Ifna5 and Ifnb, ISG-driven antiviral effectors Mx1, Oas1, and Viperin, and pro-inflammatory mediators Cxcl10 and Il6." (PMID 38742107, 2024). "Notably, IL-6 was also the most elevated in the polarized group for both infection types, albeit not to the level of statistical significance." (PMID 39162542, 2024). "Thus far, there have been no reports of such infections in clinical trials and post-marketing investigation of tocilizumab, a drug that inhibits IL-6 signaling." (PMID 38251210, 2024). "Furthermore, we evaluated whether these novel biomarkers correlated with older biomarkers, such as interleukin-6 (IL-6), glucose, and lactate dehydrogenase (LDH), used to detect intra-amniotic FIRS or infection." (PMID 39227528, 2024). "CRP, ESR, WBC, and IL-6 are not accurate enough to conclude that an infection is present or not, but they indicate there might be an infection and should be used as supplements to other outcome measurements." (PMID 39452605, 2024). "However, in the IAI group, IL‐6 was consistently at high levels during the anti‐infection process without any significant different (all p > 0.05)." (PMID 38967137, 2024). "Similarly, the R77Q infection failed to induce high levels of IL-6 as seen with the WT infection (p = 0.02), and there was no statistical difference between R77Q and Null (p = 0.14)." (PMID 39459974, 2024).
infection (continued). "In contrast, IL-12, which is indispensable for the development of adaptive immunity, may be secreted at later stages of infection and may not exhibit concurrent expression with IL-6." (PMID 38698289, 2024). "While IL-6 was essential for the awakening and the initial marked expansion of dormant DCC, minimal levels of IL-6 were detected in BALF of MMTV-Her2 mice 15 dpi, suggesting the presence of other factors that promote survival post-expansion of DCC at later times post-infection." (PMID 38645169, 2024). "Pretreatment of IPEC-J2 cells (on insert membranes) followed by a 2 h infection with ETEC resulted in decreased mRNA levels for IL-1β, TLR5 (P < 0.001), and MyD88 (P < 0.05), but increased mRNA levels for IL-8, TNF-α (P < 0.001), and IL-6 (P < 0.01) compared to the control group of IPEC-J2 cells." (PMID 37875712, 2024). "CRP, IL-6, SFLC levels and IDO activity are not independently associated with survival in this setting, likely because these are predominantly a product of chronic immune stimulation due to longstanding/recurrent infections in people living with HIV." (PMID 38633747, 2024). "We also note that serum IL-6 is not a specific marker for SBP and might be associated with many inflammatory triggers including cancer, injury and other types of infections." (PMID 38962151, 2024). "Previous studies reported that an increase in serum IL-6 levels in BDL rats without any obvious signs of infection may suggest the activation of the pro-inflammatory response similar to that observed in cirrhotic patients." (PMID 39391493, 2024). "When infected with M. tuberculosis H37Rv, an equivalent expression of Il1b and Il6 was detected in mMettl14f/f and mMettl14−/− at 4 h post-infection, indicating that Mettl14 may not regulate macrophages inflammatory response." (PMID 38548762, 2024). "Additionally, elevated levels of the cytokines IL-1β and IL-6 were observed in the cerebrospinal fluid of these patients before seizure onset despite the absence of infection." (PMID 39006838, 2024). "It has been reported that, after infection with G. parasuis, the expression of p38, ERK, and JNK increased in porcine alveolar macrophages (PAMs) via the NF-κB and MAPK signaling pathways, leading to the upregulation of inflammatory cytokines such as IL-1α, IL-1β, IL-6, IL-8, and TNF-α." (PMID 38927100, 2024). "In addition, the same study showed that the infection of the extracts could prevent SARS-CoV-2 spike pseudotyped lentiviruses and prevent the initiation of the cytokine storm by lowering the levels of IL-6 triggered by the viral infection." (PMID 38543686, 2024). "Interestingly, though knockdown of SIRT1/3 attenuated Salmonella proliferation in macrophages, in in vivo mice model of infection, inhibition or knockdown of SIRT1/3 led to more dissemination and higher organ burden, which can be attributed to enhanced ROS and IL-6 production." (PMID 39693143, 2024). "Upon infection with Brucella or in response to Brucella lipoproteins, such as the lipidated outer membrane protein 19 (L-Omp19), macrophages release inflammatory mediators such as TNF-a, interleukin-6 (IL-6), and IL-1β in a toll-like receptor 2-dependent manner (TLR2)." (PMID 38276100, 2024). "Acute pro-inflammatory cytokines including interleukin-6 (IL-6), interleukin-1β (IL-1β) and tumour necrosis factor-α (TNF-α) play a crucial role in the activation of neutrophils, T cell differentiation and control of the fever response in response to infection." (PMID 37055674, 2024). "In addition, the expression of CCL2, CXCL10 and IL-6 represented a non-significant difference with the infection of SC16, HN10 and CVS-11." (PMID 39273091, 2024). "The initial response to infection is crucial for pathogen clearance, however, this response spirals into a SIRS, characterized by an excessive release of pro-inflammatory cytokines such as interleukin-1 (IL-1), interleukin-6 (IL-6), and tumor necrosis factor-alpha (TNF-α)." (PMID 39712033, 2024).
infection (continued). "However, in addition to IL-12, GRA24 upregulates several other proinflammatory cytokines and chemokines, including IL-6, TNF, MCP-1, CCL5, CXCL1, and CXCL10 that could contribute to the lethal outcome of infection." (PMID 39440975, 2024). "Furthermore, TP3 therapy reduced the activation of pro-inflammatory cytokines TNF-α, IL-6, and CXCL5 at the infection site, indicating that it may have been used in the healing of wounds." (PMID 38741875, 2024). "Therefore, IL-6 alone is an excellent predictor of postoperative infection without the need for combined PCT and CRP levels, eliminating the needless testing and saving the hospital expenses." (PMID 38504206, 2024). "However, the authors did not assess pre-infection BP status and found no IL-6 increase in their cohort." (PMID 38424126, 2024). "We did not observe any changes in the levels of IL-6 secreted after 48 h of infection." (PMID 38698289, 2024). "In addition, quercetin inhibits the infection ability of Epstein-Barr virus (EBV) and also attenuates the resistance to drug therapy, by activating Stat3 receptor and reducing the levels of interleukin-6 (IL-6) and reactive oxygen species (ROS), key factors in B-cell survival." (PMID 39173044, 2024). "Compared to the non-infection group, we observed elevated levels of the majority of measured cytokines (25/48) in the CSF during Mtb infection, including TNF-α, IFN-γ, IL-1β, IL-2, IL-3, IL-6, IL-8, IL-10, IL-12(p40), IL-17A, IL-18, IP-10, MIG, MCP-3, MIP-1α, and MIP-1β." (PMID 38047697, 2024). "Moreover, interleukin 6 (IL-6), being a pro-inflammatory cytokine inducing CRP production and mediator of the acute phase response to infection, has been described to increase in case of PD, which might influence comorbidities." (PMID 39717783, 2024). "IL-6 levels did not increase significantly compared to other infection indicators, which may be related to missing detection in some samples." (PMID 39533550, 2024). "In accordance with the relevant pathological changes, the selected proinflammatory cytokines, including IL-1β, IL-6, and TNF-α, in the infected mice were obviously elevated at 1–3 days post-infection and then maintained a slight upregulation at lower levels at 5 and 7 days post-infection." (PMID 38338106, 2024). "Furthermore, a significant reduction was observed in IL-6 secretion by RAW264.7 cells exposed to the C48-ΔPMCNA_RS00975 mutant strain compared with those exposed to wild-type and complemented strains 3 to 12 h post-infection." (PMID 39473924, 2024). "Among 27 different mediators tested, only the secretion levels of interleukin (IL)-6, IL-8, IP-10, and Granulocyte colony stimulating factor (G-CSF) were significantly increased by EBOV infection at day 2 (p < 0.05, or p < 0.0001) post infection when a high infective dose was used." (PMID 36731656, 2023). "Our strategy was to express the mouse il-6 gene under the promoter of LISP2 selected for its unique profile expression which is limited to the mid‐to‐late liver stage, as analysis by RT-qPCR showed that LISP2 expression peaked at 48 hpi, and gradually decreased until reaching 60 h post infection." (PMID 37143657, 2023). "The present study investigated whether SaaS mediated the secretion of cytokines in vivo, with the interleukin (IL)-1β, IL-6, IL-18, tumor necrosis factor-α (TNF-α), inducible nitric oxide synthase (iNOS) and cyclooxygenase-2 (COX-2) levels in colon after infection examined with ELISA or RT-qPCR." (PMID 37158502, 2023). "Notably, asymptomatic infection of GCRV at 18°C barely induced the expression of IL6, while the higher temperature of 28°C infections significantly induced their expression, suggesting that GCRV exploits IL6 signaling to facilitate its infection at 28°C." (PMID 37099596, 2023). "Furthermore, we observed that villi pre-treated with rP21 with subsequent infection with T. gondii did not alter IL-4 and IL-6 production in relation to villi infected or not with T. gondii." (PMID 37915581, 2023).